ROBO4 (roundabout guidance receptor 4)
Diseases named in the same sentence as ROBO4 in open-access papers (continued):
Sharing a sentence is not in itself a finding about the gene and the disease.
endotoxemia (2 papers, 2024). "In endotoxemia, vascular permeability is reduced when Robo4 expression is upregulated by Smad signaling." (PMID 38383474, 2024). "In endotoxemia and infectious disease models, Robo4 suppresses vascular hyperpermeability and mortality induced by lipopolysaccharide, Escherichia coli, influenza virus, and SARS-CoV-215,19,22, indicating that ROBO4 is a promising therapeutic target for infectious and inflammatory diseases." (PMID 38762541, 2024).
Hypertension (2 papers, 2019 to 2026). The presence of chronic increased pressure in the systemic arterial system. "In summary, although a Robo4 vaccination did not affect wound healing and organ integrity in tumor-bearing mice models, clinical evidence for the ability of Robo4-targeting strategies to avoid the known adverse effects of anti-VEGF therapy, namely, hypertension and proteinuria, is unavailable." (PMID 31160487, 2019).
non-small cell lung carcinoma (2 papers, 2015 to 2016). A group of at least three distinct histological types of lung cancer, including non-small cell squamous cell carcinoma, adenocarcinoma, and large cell carcinoma. "Increased expression of ROBO4, CLEC14A and ECSCR have also been associated with improvements in survival in non-small cell lung cancer." (PMID 26943033, 2016).
proliferative diabetic retinopathy (2 papers, 2009 to 2019). Advanced retinopathy due to diabetes mellitus characterized by the formation of new vessels in the retina. "This study determined the colocalization of VEGF and Robo4 in fibrovascular membranes (FVM) from patients with proliferative diabetic retinopathy (PDR)." (PMID 30980286, 2019). "In our previous study, Robo4 was found upregulated in human retinal endothelial cells under hypoxia and overexpressed in the FVMs from proliferative diabetic retinopathy (PDR) patients." (PMID 30980286, 2019). "This study investigated the effect of Robo4 on the formation of fibrovascular membranes (FVMs) from patients with proliferative diabetic retinopathy and its roles in choroid–retina endothelial (RF/6A) and human retinal pigment epithelial (RPE) cells." (PMID 19495426, 2009). "In this study, we demonstrated for the first time that Robo4 mRNA is expressed in the FVMs of human eyes with proliferative diabetic retinopathy." (PMID 19495426, 2009).
acute kidney injury (1 paper, 2014). Sudden and sustained deterioration of the kidney function characterized by decreased glomerular filtration rate, increased serum creatinine or oliguria. "We investigated the hypothesis that plasma levels of Robo4 are indicative of organ injury, in particular acute kidney injury (AKI), after cardiac surgery." (PMID 25360813, 2014).
Arthritis (1 paper, 2024). Inflammation of a joint. "Taken together, these results indicated that Robo4 suppressed Ptgs2-associated inflammatory conditions such as arthritis, edema, and pain." (PMID 38762541, 2024). "In the arthritis model, Robo4-deficient (Robo4−/−) and wild-type (Robo4+/+) mice were subcutaneously injected with type II collagen with Freund’s complete adjuvant twice, and their rheumatoid arthritis scores were subsequently assessed according to the evaluation criteria." (PMID 38762541, 2024). "Moreover, we revealed that ROBO4 partially suppresses PTGS2-associated inflammatory diseases, including arthritis, edema, and pain in mouse models." (PMID 38762541, 2024). "In addition, Robo4-deficiency in mice exacerbates PTGS2-associated inflammatory diseases, including arthritis, edema, and pain." (PMID 38762541, 2024).
ascending aortic aneurysm (1 paper, 2021). "The involvement of ROBO4 in BAV formation and in BAV-associated ascending aortic aneurysm was confirmed using animals deficient for Robo4 as well as by endothelial cell-specific Robo4 silencing or mutation." (PMID 34071740, 2021).
atherosclerosis (1 paper, 2023). A disease characterized by the build-up of fatty material and calcium deposition in the arterial wall resulting in partial or complete occlusion of the arterial lumen. "This study showed that Robo4 expression was significantly decreased in the aorta of ApoE−/− mice with atherosclerosis induced by HFD feeding and that oral administration of RS significantly suppressed the decrease in Robo4 expression." (PMID 37998401, 2023).
atrial septal defect (1 paper, 2023). Interauricular communication is a congenital malformation characterized by a communication between the atrial chambers of the heart. "ROBO4 variants were also identified in individuals with AVS and atrial septal defect (ASD)." (PMID 37187784, 2023).
bladder cancer (1 paper, 2023). "In the blood vessels of some tumors, such as ganglioglioma and bladder cancer, ROBO4 was highly expressed, and vaccination against ROBO4 has been shown to inhibit angiogenesis and retard tumor growth." (PMID 37430272, 2023).
dementia (1 paper, 2023). Loss of intellectual abilities interfering with an individual's social and occupational functions. "This study highlights the necessity to evaluate the risk of brain vascular impairment and dementia in female patients and in patients with ROBO4 variants." (PMID 37675802, 2023).
endothelial dysfunction (1 paper, 2014). In vascular diseases, endothelial dysfunction is a systemic pathological state of the endothelium (the inner lining of blood vessels) and can be broadly defined as an imbalance between vasodilating and vasoconstricting substances produced by (or acting on) the endothelium. "We (and others) have hypothesised that Robo4 could be a clinically useful marker of endothelial dysfunction." (PMID 25360813, 2014).
gestational diabetes (1 paper, 2023). Carbohydrate intolerance first diagnosed during pregnancy. "The clinical resume of the ToF-patient (ToF-PED-9) carrying the ROBO4: p.Arg776Cys variant is as following: Pregnancy was complicated by gestational diabetes." (PMID 36855159, 2023).
kidney tumour (1 paper, 2008). "In the tumour screen, ROBO4 was seen to be tumour specific in brain and kidney tumour tissues but not at a statistically significant level." (PMID 18394197, 2008).
metastatic disease (1 paper, 2017). "As the major clinical challenge is systemic control or cure of multi-organ metastatic disease, we tested the RGD.H5/3.ROBO4-EGFP reporter vector administered intravenously to NSG mice bearing IGR-CaP1 experimental bone and visceral metastases 4 weeks post intracardiac administration." (PMID 28103576, 2017).
ovarian carcinoma (1 paper, 2011). A malignant neoplasm originating from the surface ovarian epithelium. "Basal SLIT2, SLIT3, ROBO1, ROBO2 and ROBO4 expression was lower in primary cultures of ovarian cancer epithelial cells when compared to normal OSE (P<0.05) and in poorly differentiated SKOV-3 cells compared to the more differentiated PEO-14 cells (P<0.05)." (PMID 22132142, 2011).
pulmonary hypertension (1 paper, 2012). Increased pressure within the pulmonary circulation due to lung or heart disorder. "Our data strongly support their function in Robo4-mediated lymphatic permeability upon HIV-1 gp120 stimulation, and imply a potential role for Robo4 in fibronectin-associated vasculopathies, such as HIV-associated pulmonary hypertension." (PMID 22241990, 2012).
retinopathy of prematurity (1 paper, 2016). A bilateral retinopathy characterized by neovascularization, scarring, retinal detachment, and eventually blindness. "The data suggest that promoting Y951 activation via ROBO4 blockade might represent an opportunity to enhance ocular revascularization in retinopathy of prematurity and wound healing in diabetic patients." (PMID 27882935, 2016). "We conclude that Robo4 inhibits angiogenesis and vessel permeability independently of its cytoplasmic domain, while activating VEGFR2-Y951 via ROBO4 inhibition might accelerate tissue revascularization in retinopathy of prematurity and in diabetic patients." (PMID 27882935, 2016).
situs inversus (1 paper, 2023). A congenital condition in which there is complete right-to-left reversal of the position of the major thoracic and abdominal organs (that is, they are arranged in a mirror image of the normal positioning). "The clinical resume of the ToF-patient (ToF-PED-11) carrying the ROBO4: c.3001 + 3G > A splicing variant is as following: Severe ToF and thoraco-abdominal situs inversus was prenatally diagnosed." (PMID 36855159, 2023).
thoracic aortic aneurysm (1 paper, 2023). An aneurysm formed in the wall of the proximal portion of the descending aorta proceeding from the arch of the aorta. "Although roles of ROBO4 in developmental angiogenesis remains controversial, ROBO4 variants are linked to a congenital defect, the bicuspid aortic valve, which frequently accompanies thoracic aortic aneurysm." (PMID 36942388, 2023).
type 2 diabetic (1 paper, 2026). "Results suggest that elevated serum KNG-1, HSPG and Robo4 levels in type 2 diabetic patients might reflect a DN progressive pathology due to various mechanisms." (PMID 42310331, 2026).
tumor (32 papers, 2006 to 2025). "In a tumor environment, Robo4 has been implicated to regulate the migration of endothelial cells during tumor angiogenesis." (PMID 28389649, 2017). "Despite limited research on the SLIT/ROBO pathway in PCa, a recent study showed that the expression of ROBO4 was associated with higher tumor histological grade; however, patients with high ROBO4 expression exhibited lower biochemical recurrence, possibly reflecting a protective role for ROBO4." (PMID 40508075, 2025). "Of note, higher histological tumor grade was correlated with the increased expression of ROBO4, while controversial patients with high ROBO4 showed lower recurrence, suggesting its protective role." (PMID 40136513, 2025). "One significant finding in this study is that Robo4 is expressed not only in vascular endothelial cells, but also in many human tumor cells in many tumor types." (PMID 35740295, 2022). "We therefore focused on roundabout homolog 4 (Robo4), which is expressed in tumor vascular endothelial cells at high levels, as a novel target molecule." (PMID 35740295, 2022). "mRNA levels of SLIT2, ROBO2, ROBO3, ROBO4 were significantly downregulated in tumor tissues compared to normal tissues." (PMID 35053460, 2022). "Since tumor microenvironments are typically hypoxic, it is possible that this is the reason why Robo4 was expressed in tumor cells." (PMID 35740295, 2022). "Considering that CAR-T cells can only act on proteins on the cell membrane, it will be necessary to confirm the localization of Robo4 expression in tumor-cell suspensions immediately following disaggregation." (PMID 35740295, 2022). "The plasma membrane protein, ROBO4, serves as a therapeutic target in tumour endothelial cells; ROBO4 conjugates suppress tumour angiogenesis and growth." (PMID 32626543, 2020). "Tumor endothelial-specific expression of Robo4 in adults reveals that this plasma membrane protein represents an antitumor target for immunotherapeutic approaches, such as vaccination." (PMID 31160487, 2019). "Robo4 vaccination with alum adjuvant, a mild inducer of Th2-dependent antibody responses, also reduced tumor growth via an antibody-mediated mechanism, particularly an IgG1-mediated mechanism, instead of cytotoxic T-cell responses." (PMID 31160487, 2019). "The fourth Robo4 targeting therapy conjugates the high cell-internalizing anti-Robo4 antibody with anticancer drugs and targets the tumor vascular with high specificity and efficiency." (PMID 31160487, 2019). "Because Robo4 expression is restricted to sites of active angiogenesis, including blood vessels in tumors, it represents a potential marker of the tumor vasculature when conjugated with anticancer drugs." (PMID 31160487, 2019). "TEM have been shown to be selectively expressed by tumor endothelial cells and to have important biological functions (e.g. Robo4 inhibits VEGFR2 signaling)." (PMID 26956051, 2016). "Robo1 is mainly present in tumor cells, whereas Robo4 is located primarily in endothelial cells of tumor vessels in CRC." (PMID 25605242, 2015). "Robo4 is pathologically over-expressed in the tumor endothelium, it promotes atypical vascular patterning that reduces blood-tumor barrier permeability, thereby likely impeding the access of chemotherapy drugs to tumors." (PMID 26510973, 2015). "Robo4 is involved in hematopoietic stem/progenitor cell homeostasis and essential for tumor angiogenesis." (PMID 25794001, 2015). "In this review we have summarized the molecular mechanism of developmental and pathological angiogenesis mediated by magic roundabout (ROBO4) as one of the major processes supporting the tumor growth." (PMID 24689049, 2014). "While ROBO1 is expressed in both endothelial cells and other cell types, ROBO4 is expressed specially in vascular endothelial cells including the tumor vasculature." (PMID 24689049, 2014).
tumor (continued). "Based on this vascular density analysis, we immunoblotted for the EC specific marker, VE-cadherin in our ROBO4 immunoblots and all subsequent Westerns to normalize for this differential tumor/host organ vascular density." (PMID 24376772, 2013). "Similar to function, it has been challenging to discern a literature consensus on differential ROBO4 expression in tumor versus host ECs." (PMID 24376772, 2013). "Compared to prior reports suggesting robust ROBO4 upregulation in tumor angiogenesis, endogenous ROBO4 was very modestly upregulated 2.0-fold in KO, and 1.4-fold in SC 786-O tumors, compared to liver." (PMID 24376772, 2013). "ROBO4 has been suggested to be a tumor EC specific marker with minimal to undetectable expression in host ECs." (PMID 24376772, 2013). "In liver tissues, differential expression of ROBO1, ROBO4 and SLIT2 was found to be associated with clinicopathological parameters such as tumor staging and differentiation." (PMID 19114000, 2008). "We also observed a down-regulated ROBO4 expression in tumor tissues with a p-value near significance (MeanNormal = 0 ± 1.03, MeanTumor = -0.89 ± 1.30; p = 0.079)." (PMID 19114000, 2008). "Interestingly, in both groups, many of the pathways associated with tumor angiogenesis (VEGFA-VEGFR2, Robo4 and VEGF crosstalk, angiogenesis, and neovascularisition) were significantly upregulated." (PMID 36835505, 2023). "Therefore, similarly to VEGFR2, which is expressed on vascular endothelial cells, Robo4 is a candidate target for tumor vascular injury-type CAR-T cells promoted by our group." (PMID 35740295, 2022). "Since most tumors induce angiogenesis, we constructed CAR-T cells targeting roundabout homolog 4 (Robo4), which is expressed at high levels in tumor vascular endothelial cells, by incorporating three anti-Robo4 single-chain variable fragments (scFv) that were identified using phage display." (PMID 35740295, 2022). "Therefore, preliminary assessment of Robo4 expression was conducted via immunofluorescence using a human normal/tumor tissue panel array." (PMID 35740295, 2022). "Therefore, we investigated the effect of Robo4-specific CAR-T cell therapy when targeting both tumor blood vessels and cancer cells using L1.2 cells in which mRobo4 was forcibly expressed." (PMID 35740295, 2022). "ROBO1 and ROBO4 were found to express in the vascular endothelial cells and may have some role in tumour angiogenesis, but very little is known to date." (PMID 33318575, 2020). "In conclusion, high concentrations of inflammatory cytokines such as TNFα may induce Robo4 expression in ECs located in sites of inflammation and tumor vessels." (PMID 31160487, 2019). "Biased tumor vascular endothelial expression was achieved with the use of the human ROBO4 promoter." (PMID 28103576, 2017). "The anti-tumor effect of Robo4 vaccination was present in CD8 deficient mice but absent in B cell or IgG1 knockout mice, suggesting antibody-dependent cell mediated cytotoxicity as the anti-vascular/anti-tumor mechanism." (PMID 25889119, 2015). "Expression of ROBO4 at the site of neoangiogenesis suggests its involvement in tumor growth." (PMID 24689049, 2014). "Whole tumor ROBO4 expression assays revealed either induction or downregulation." (PMID 24376772, 2013). "Furthermore, ROBO4 was overexpressed in tumor endothelial cells in comparison to normal adult endothelial cells." (PMID 19114000, 2008). "Moreover, Fisher's pairwise comparison analyses revealed that ROBO1, SLIT2 and ROBO4 significantly discriminated between different histopathological subgroups both in terms of differentiation status and/or tumor staging." (PMID 19114000, 2008). "Finally, to target tumor angiogenesis to block neo-vessel formation and impair tumor progression, studies have shown that it is possible to target proliferative vascular endothelium using the ROBO4 (Roundabout Guidance Receptor 4) promoter." (PMID 36678835, 2023).
tumor (continued). "Robo4 is differentially expressed between the normal and tumor vasculature, indicating that Robo4 expression may reflect tumor angiogenesis and become a potential target for tumor therapy." (PMID 31160487, 2019). "Thus, Robo4 expression and its clinical importance vary among cancers, and Robo4 may be a potential marker for disease progression during treatment with anti-tumor therapies." (PMID 31160487, 2019). "Since ROBO4 has dual behaviour of promoting and inhibiting angiogenesis depending on cell/tissue type, the therapeutic agents having properties of promoting and inhibiting ROBO4 signalling, respectively, can be used to target tumor angiogenesis according to the cell/tissue type under consideration." (PMID 24689049, 2014). "High cell-internalizing monoclonal antibodies against Robo4 and VEGFR2 have been isolated and showed higher tumor accumulation and antitumor effects as antibody–drug conjugates (ADC)." (PMID 31160487, 2019). "In the network, Slit2 and Slit3 were redundantly activating Robo1, Robo2, Robo4 and ITGA1 receptors in tumor." (PMID 24597571, 2014). "We also provide quantitative evidence for potential use of ROBO1, ROBO4 and SLIT2 for prediction of tumor stage and differentiation status." (PMID 19114000, 2008). "According to earlier views ROBO4 inhibits the migration of heterologous cells (that express ROBO4) and primary endothelial cells by interacting with SLIT2, resulting in downmodulation of tumor growth." (PMID 24689049, 2014). "In tissue expression analyses, we found that ROBO4 expression is significantly down-regulated in poorly differentiated tumors, indicating that ROBO4 function is not essential for the maintenance of tumor at this step of hepatocarcinogenesis." (PMID 19114000, 2008). "Therefore, the results clarified that the strength of CAR-T cell function in vitro is not always reflected at high Robo4 expression levels in tumor tissue." (PMID 35740295, 2022). "Importantly, at disease progression, we observed an increase of proangiogenic factors, upregulation of CEC/CEP levels and downregulation of TEMs, such as Robo4 and endothelial cell-specific chemotaxis regulator (ECSCR), reflecting the formation of torturous tumor vessels." (PMID 26956051, 2016). "ROBO4 was found to be selectively expressed on tumor endothelial cells but not healthy vasculature." (PMID 25889119, 2015). "Five genes, ROBO4, SNRK, TM4SF1, FMO2 and TIMP3, found in this screen have been preferentially associated with capillary endothelial cells from mouse lung and TMBM expression was found specifically in tumour endothelial cells, but not normal endothelial cells." (PMID 16390543, 2006). "Thus ROBO4 was predicted as a tumour endothelial marker, but not in all tumour types." (PMID 18394197, 2008). "Finally, TRAF7’s involvement in multiple signaling pathways (e.g., MEKK3-ERK5, NF-κB, Robo4) poses a challenge for therapeutic targeting, as perturbation of TRAF7 could lead to unintended effects in other cellular contexts, such as immune modulation or tumor suppression." (PMID 40868928, 2025).